EGFR (epidermal growth factor receptor)
Diseases named in the same sentence as EGFR in open-access papers (continued):
Sharing a sentence is not in itself a finding about the gene and the disease.
infection (continued). "By using confocal microscopy, we also found the cytoskeleton rearrangement in hBMECs during S. suis infection, and similarly, we observed that the infection-activated cellular EGFR competitively recruited ACTN4 from F-actin, which accounts for the infection-induced cytoskeleton disturbance." (PMID 30687645, 2018). "Here, by comparing the anti-EGFR immunoprecipitation products from cells with or without infection, we identified ACTN4 as an interacting protein for EGFR." (PMID 30687645, 2018). "We therefore used EGR1 upregulation as a marker for EGFR activation and examined whether T4SS or CagL is involved in the activation of EGFR during infection." (PMID 29468142, 2018). "To investigate whether EGFR also plays a role in the induction of IL-8 by H. pylori during infection of HUVECs, we pre-treated HUVECs with AG1478 prior to infection with H. pylori." (PMID 29468142, 2018). "Indeed, HCV not only requires EGFR signaling but also actively induces the activation of this pathway during HCV binding and infection and prolongs EGFR signaling by perturbing EGFR degradation via NS5A, as reported upon its ectopic expression." (PMID 30279347, 2018). "To determine whether EGFR affects the process of TGEV invasion and infection of IPEC-J2 cells, we used Western blotting to assess its levels in TGEV-infected cells." (PMID 30483239, 2018). "Through real-time PCR, we have shown that ADAM17 was the key player in mediating EGFR activation, by the demonstration that ADAM17 inhibitor TAPI-1 treatment significantly suppressed the infection-induced transactivation of EGFR by preventing the proteolysis and secretion of HB-EGF." (PMID 30687645, 2018). "Dimerization and transactivation of EGFR require interactions to occur with its specific ligands, one of which has been identified herein as HB-EGF in hBMECs with meningitic E. coli PCN033 infection." (PMID 30687645, 2018). "Moreover, the induction of EGFR and amphiregulin occurred at later time points than that for EGR1, i.e., at 4–6 h post infection." (PMID 28180113, 2017). "In conclusion, the use of EGFR-TKIs significantly increased the risk of developing all-grade infectious events in NSCLC patients, but not for severe and fatal infections." (PMID 28107192, 2017). "The result shows that the peto OR of all-grade infections tends to be increased with EGFR-TKIs treatment duration, but it is not statistically significant (p = 0.26)." (PMID 28107192, 2017). "We have previously reported that pUL135 and pUL138 also localize to the VAC during infection; however, we did not observe any difference in the localization of pY1068 EGFR between WT, UL135STOP or UL138STOP infections." (PMID 27218650, 2016). "Treatment of H292 cells with increasing concentrations of EGFR inhibitor AG1478 resulted in a dose-dependent reduction in infectivity of all three virus strains at an MOI of 1, and the reduction in infection was greater against A2-2-20F and A2-2-20GF than against A2." (PMID 27152417, 2016). "By contrast, UL138 expression alone upregulates surface expression of TNFR1 and confirmed in S1 Fig, suggesting that UL138 requires other infection-specific factors for the regulation of EGFR, but not TNFR1." (PMID 27218650, 2016). "While EGFR and PI3K activation has been shown to be important for entry of HCMV into fibroblasts and monocytes, nothing is know about the role of EGFR throughout infection." (PMID 27218650, 2016). "Therefore, we conclude that EGFR and the attaching TGEV particles are located together in the lipid rafts during infection." (PMID 26933809, 2016). "Surface levels of EGFR in UL138STOP did not change significantly relative to WT infection on uninfected cells." (PMID 27218650, 2016). "In the context of infection, we confirmed interaction between EGFR and pUL135 or pUL138, but not another myc-tagged protein from the UL133/8 locus, pUL133MYC." (PMID 27218650, 2016).
infection (continued). "Until recently, the infections observed during treatment with EGFR- or HER-2-directed antibodies had not been attributed to the administration of the antibodies themselves." (PMID 25857245, 2015). "As shown in a previous study, EPEC-mediated activation of EGFR can be observed as early as 15 min post-infection in EPEC-treated non-polarized Caco-2 cells, whereas EGFR phosphorylation in polarized Caco-2 cells is not evident until 4 h after infection." (PMID 25915861, 2015). "Previous studies have identified several cellular proteins that may function at early steps of infection, including platelet-derived growth factor receptor-α (PDGFR-α), epidermal growth factor receptor (EGFR), DC-SIGN, αVβ3 and β1 integrins, and paxillin." (PMID 26147640, 2015). "In addition, overexpression of miR-205-5p in BCSC #1 cells by infection with pCMV-RFP-2A-puro lentivector results in strongly reduced protein levels and in reduced mRNA levels of both ErbB2 and EGFR." (PMID 26181203, 2015). "Permissiveness to infection correlated with induction of the liver-specific microRNA-122 and modulation of cellular factors that affect HCV replication, such as epidermal growth factor receptor (EGFR), ephrin receptor A2 (EphA2), and phosphatidylinositol 4-kinase type III alpha (PI4KIIIa)." (PMID 26184286, 2015). "The Hsp60 antigen load in the cells infected with drug-treated EBs was comparable to the infection by the untreated EBs, confirming that EGFR inhibitors did not affect the viability of EBs in these experiments." (PMID 25471819, 2014). "Ectopic expression of EGFR in EGFR-negative hamster cells leads to binding of Pmp21 beads and EBs, thus boosting the infection." (PMID 23633955, 2013). "Blocking MEK1/2 or PI3 kinase activity reduced EB internalization and infection but not EB binding, proving the relevance of this EGFR-mediated signaling pathway for chlamydial entry (this work)." (PMID 23633955, 2013). "However, in the present study, forced expression of IGFBP-3 by infection with an adenoviral vector or addition of recombinant IGFBP-3 only slightly increased the growth-inhibitory and apoptotic effects of EGFR-TKIs." (PMID 24339922, 2013). "Interestingly, infection with the ΔcadF mutant, as examined under identical conditions, revealed that phosphorylation of FAK, EGFR and PDGFR were widely impaired and correlated with the reduced invasiveness of this mutant." (PMID 22204307, 2011). "We further demonstrated that infection of wild-type cells induces increasing amounts of phosphorylated FAK and growth factor receptors (EGFR and PDGFR) during the course of infection, correlating with accumulating Cdc42-GTP levels and C. jejuni invasion over time." (PMID 22204307, 2011). "As a consequence, flies with reduced EGFR activity in ISCs failed to repair their guts following infection, and they died within 10-14 days." (PMID 21176204, 2010). "This was also visible by reduced infection upon inhibiton of the EGFR kinase prior to infection applying either the PD-inhibitor or Lapatinib, an additional EGFR inhibitor (data not shown)." (PMID 20844577, 2010). "Conversely, the overexpression of the EGFR pathway in enterocytes induced high levels of cell delamination in the absence of infection." (PMID 21176204, 2010). "Thus, the EGFR and attaching IAV particles are localized to lipid raft domains that are reorganized upon infection." (PMID 20844577, 2010). "We observed the mRNA level of EGFR to be up-regulated, and downstream signaling protein, such as STAT3, STAT1, AKT3 and MKK4 also showed up-regulation at 4 days post infection." (PMID 21172007, 2010). "In contrast, PilC2-mediated infection did not notably affect EGFR levels in the host cells despite binding efficiently." (PMID 19718432, 2009). "In contrast, PilC2-mediated infection did not notably affect the EGFR pathway, and these specificities were shared among unrelated meningococcal strains." (PMID 19718432, 2009).
infection (continued). "Having established that VGF-mediated survival depends on the EGFR, we next asked whether exogenously supplied VGF is sufficient to rescue F1L-independent cell survival during ΔF1L/VGF infection." (PMID 19388902, 2009). "However, according to Western blot analysis in A549 cells, the total amount of EGFR does not change during infection (insert)." (PMID 40362195, 2025). "Further investigations found several factors, such as the epidermal growth factor receptor (EGFR), phosphoinositide 3-kinase (PI3Ks), p21-activated kinase-1 (PAK1), Niemann-Pick C1 (NPC1), and NPC2, as potential factors in ASFV entry, highlighting the complexity of ASFV infection mechanisms." (PMID 39943192, 2025). "Our findings extend these observations by highlighting that modulation of growth factor receptor signaling, particularly EGFR, PDGFR, and VEGFR, may offer therapeutic benefit in reversing the CVB3-infected iBEC transcriptome during the later stages of infection." (PMID 40806174, 2025). "Our observation that gefitinib treatment did not alter the infection-induced accumulation of HIF1α suggests that HIF1α activation occurs independently of EGFR signaling, however, further experiments are required to understand the interplay, if any, between HIF1α, EGFR and Integrin α3β1." (PMID 38902255, 2024). "EGF stimulation induced the internalization of EGFR in both cell types, irrespective of infection." (PMID 38856640, 2024). "Notably, HBCs also upregulate amphiregulin in response to LM, which may activate the epidermal growth factor receptor (EGFR) on trophoblasts, potentially supporting their survival and regeneration after infection." (PMID 39458411, 2024). "Apparently, as a result of infection with S. grimesii, Ca2+ accumulates in the host cells and may activate the ADAM10 sheddase, which can promote invasion by cleaving E-cadherin and, as a result, triggering EGFR signaling." (PMID 38069398, 2023). "In the early stage of infection of Eimeria species, the opening of mitochondrial permeability transition pore (MPTP) and the decrease in transmembrane potential were activated; the Akt and ERK proteins, key factors of the epidermal growth factor receptor (EGFR) signaling pathway, were upregulated." (PMID 38136854, 2023). "Apparently, as a result of infection with S. grimesii, Ca2+ accumulates in the host cells and may activate ADAM10 sheddase, which can promote invasion by cleaving E-cadherin and, as a result, triggering EGFR signaling." (PMID 38069398, 2023). "During the initiation and propagation stages of infection, several renin-angiotensin system (RAS) family genes (e.g., ACE2 and ANPEP) are upregulated, whereas others (e.g., epidermal growth factor receptor - EGFR and insulin-like growth factor 2 receptor - IGF2R) are downregulated." (PMID 38813031, 2023). "EGFR inhibition using gefitinib and erlotinib, or of MEK1/2 (using UO126), dose-dependently decreased the vanadate-enhanced growth of VSVΔ51 tagged with a GFP marker in 786-0 cells as determined by phase and fluorescent microscopy images captured 24 h post infection (hpi)." (PMID 35572196, 2022). "In addition, ectopic EGFR expression is necessary and sufficient for permissive infection of an IL-3-dependent hematopoietic progenitor cell line lacking endogenous EGFR with AAV6, but not with other AAV serotypes." (PMID 35083168, 2021). "For example, interaction networks highlight the multifaceted role epidermal growth factor receptor (EGFR) plays in pathogenicity; it acts as a key regulator during influenza virus infection and is exploited by vaccinia virus to promote cell motility and the spread of infection in its host." (PMID 34832652, 2021). "Therefore, we propose that CD9 might regulate the local distribution of the protease ADAM17 and its EGFR-activating substrates, which then influences the organization of the HPV16 entry receptor platform and eventually infection." (PMID 32385608, 2020).
infection (continued). "Indeed, this short-lived elevation appears important in candidalysin-triggered responses, since reduced availability of ATP (via Apyrase) significantly inhibits EGFR activation, MAPK signalling (c-Fos, MKP1) and IL-6 release following infection or toxin treatment." (PMID 32178483, 2020). "While molecular and structural information is available for both HA-SA and EGFR-EGF interactions, much less is known about their spatial co-organization within the plasma membrane, and how it could enable EGFR activation during IAV cell infection." (PMID 32639985, 2020). "Beyond EGFR, UL138 also enhances levels of tumor necrosis factor-alpha (TNF-α) on the surface of infected cells, but more studies are required to define a role for UL138-mediated modulation of TNF-α in HCMV latency or in modulation of the innate response to infection." (PMID 32630219, 2020). "However, we did not detect any significant alteration in EGFR mRNA levels by quantitative reverse transcriptase PCR (RT-qPCR) over the time course of infection." (PMID 31725811, 2019). "Similarly, HAdV-B7 and HAdV-E4 did not have a discernible effect on total EGFR protein compared to HAdV-C2, following an 18 h infection." (PMID 31425554, 2019). "Thus, EGFR appears to play a significant role in the severity of non-lethal infections such that when it is inhibited, the infection is more severe." (PMID 31616667, 2019). "The utilization of EGFR during infection suggests that VACV could use the mitogenic signaling potential of EGFR to activate the MAPK-ERK cascade, yet VGF is not required for sustained ERK1/2 activation." (PMID 31336840, 2019). "Having shown that tubulation is lost in the absence of EGFR signaling, we were next interested in determining whether tubulation would be perturbed if EGFR signaling was abolished once infection had already been established." (PMID 31192164, 2019). "The predicted activation of EGFR signaling at 14 h, and not 24 h, could be indicative of a host response to the early stage of infection when R. delemar first invades the airway epithelium." (PMID 30108171, 2018). "Upon infection in EGFR(−) Chinese Hamster Ovary (CHO) cells, this virus did not induce cell fusion." (PMID 28106842, 2017). "We first checked the transcription of these ErbB members by real-time PCR and found that the transcription levels of EGFR, ErbB2, and ErbB4 did not significantly change in response to SC19 infection, while ErbB3 showed a significant decrease since 2 h post infection." (PMID 27756321, 2016). "Nevertheless, we could not exclude the possibility of EGFR homodimerization in response to SS2 infection based on our current data." (PMID 27756321, 2016). "However, during UL138STOP infection pY staining of EGFR was decreased by 60% (p-value = 0.015), suggesting that pUL138 maintains EGFR signaling during infection, but not necessarily through Y1068." (PMID 27218650, 2016). "As EGFR phosphorylation/activation mediates mucin expression in response to other respiratory viruses, RSV A2 is known to activate EGFR, and RSV 2–20 F is more “mucogenic” than A2 F in the context of infection, we hypothesized that the 2–20 strain F protein potently activates EGFR." (PMID 27152417, 2016). "Interestingly, infection of WD-PBECs with BT2a resulted in an apparent increase in surface expression of p-EGFR in RSV-infected cells, but not neighboring non-infected cells." (PMID 27152417, 2016). "However, unlike WT infection, EGFR surface levels were restored to 85% of initial levels by 60 minutes in UL135STOP infection." (PMID 27218650, 2016). "We further demonstrated that the time-dependent phosphorylation of EGFR in response to SC19 infection became attenuated in sh-ErbB3 transfected cells, and vice versa, 5 μM AG1478 treatment significantly blocked the infection-induced phosphorylation of ErbB3, compared with the vehicle control." (PMID 27756321, 2016).
infection (continued). "The activation of either PDGFR- α or EGFR in turn leads to activation of downstream cellular phosphatidylinositol 3-kinase (PI3K), Src kinase and focal adhesion kinase (FAK) signaling pathways, and induces cytoskeletal rearrangements to create an intracellular environment to facilitate infection." (PMID 26147640, 2015). "Interestingly, depletion of EGFR in HeLa cells did not reduce infection by another chlamydial species, pointing to differences in receptor usage between chlamydial species." (PMID 23633955, 2013). "Human foreskin fibroblasts (HFF) cells were very efficiently infected with HCMV TR, so that cells transduced with the control Ad-tet-trans exhibited 98% IE-86+ cells using only 1 IU/cell, and this high level of infection was not changed when cells were transduced with PDGFRα or EGFR." (PMID 23028311, 2012). "Furthermore, EGFR also displayed different patterns of phosphorylation in a kinomics comparison of pathogenic and non-pathogenic PICV infections, which was correlated with activation or inhibition of its receptor activities." (PMID 23342371, 2012). "Interestingly, the pattern of Armadillo staining did not change during infection in flies depleted of EGFR in enterocytes, but instead a weak and constant Armadillo staining was observed in enterocytes." (PMID 21176204, 2010). "Similarly to non-infected cells, PilC2-mediated infection left ME180 cells permissive for EGFR phosphorylation upon EGF stimulation." (PMID 19718432, 2009). "Taking advantage of the distinct markers used for Jurkat-S(Wuhan) and Jurkat-S(Alpha) cells (EGFR and EGFP, respectively), we could mix equal numbers of both cell lines and incubate the cell mixture with dilutions of sera from patients recovered from infection with SARS-CoV-2 or vaccinated." (PMID 37081876, 2023). "However, the mechanism by which EGFR signaling is stimulated during infection was not identified." (PMID 32487760, 2020). "Also, we could readily detect phosphorylation of EGFR Tyr845 following infection with RSV, but not following treatment with ouabain, suggestive of a quantitative or qualitative difference in EGFR phosphorylation." (PMID 31381610, 2019). "The same phosphorylation was also induced following infection with four other Mucorales species—Rhizopus oryzae, Lichtheimia corymbifera, Mucor circinelloides, and Cunninghamella bertholletiae —indicating that EGFR activation is not a strain- or species-specific phenomenon." (PMID 30108171, 2018). "The VGF peptide, in isolation, is capable of activating the EGFR pathway; however, it cannot independently phosphorylate CAD and S6K1 in the absence of infection." (PMID 39817770, 2025). "Mechanistically, AKT-sensitive phosphorylation of FOXO3a by T. gondii required live infection and the activity of PI3K but was independent of the plasma membrane receptor EGFR and the kinase PKCα." (PMID 37387601, 2023). "In summary, our results suggest that access to EGFR is critical for HEV and facilitates infection independent of its kinase activity." (PMID 36745934, 2023). "Evidence from lytic infection studies suggests that RhoA is downregulated upon HCMV interaction with EGFR at the cell surface; however, the role of RhoA in EGFR signaling during latency has not yet been demonstrated." (PMID 33824207, 2021). "Again, the infection-mediated increase in the cleaved caspase-3 level was clearly higher in PBMO than in CBMO, and inhibition of EGFR increased cleaved caspase-3 levels in infected CBMO but not in PBMO." (PMID 32082070, 2019).